AIM2 (absent in melanoma 2)
Diseases named in the same sentence as AIM2 in open-access papers (continued):
Sharing a sentence is not in itself a finding about the gene and the disease.
cancer (137 papers, 2008 to 2026). A tumor composed of atypical neoplastic, often pleomorphic cells that invade other tissues. "Among the heatmap representations of cancer-associated genes, AIM2 was significantly downregulated in P3 phRPE cells." (PMID 39870644, 2025). "Overexpression of AIM2 through STAT1/NF-κB pathway is associated with cancer progression, radioresistance, and increased PD-L1 expression, thus upregulated AIM2 predicting favorable response for ICI therapy." (PMID 41291696, 2025). "Subsequently, we conducted RNA-Seq and GSEA, which suggested that AIM2 expression was associated with some cancer-related processes and pathways, including oxidative phosphorylation, focal adhesion, cell cycle, and MAPK signaling pathways." (PMID 38186575, 2023). "Dysregulation of AIM2 has been implicated in autoimmune diseases, inflammatory disorders, and certain cancers, such as OSCC." (PMID 38067304, 2023). "Herein, we briefly outline the mechanisms underlying the activation of NLRP3 and AIM2 inflammasomes, as well as their crosstalk with autophagy in the context of cancer." (PMID 32703253, 2020). "The AIM2 inflammasome can weaken the activation of S6K1 by targeting mTOR, thus inhibiting the growth of cancer cells, and the accumulation of the AIM2 inflammasome can cause HCC cells pyroptosis, exerting antitumor effects." (PMID 31501419, 2019). "Furthermore, we discuss the potential applications and challenges associated with targeting AIM2 in cancer therapy." (PMID 39744568, 2025). "Although implicated in different types of cancer, the trigger for AIM2 in these cancers remains unknown." (PMID 37449203, 2023). "Consequently, this study endeavors to assess AIM2’s expression levels, explore its potential antitumor effects, elucidate associated cancer-related processes, and decipher the underlying signaling pathways in CRC." (PMID 38186575, 2023). "Our data surprisingly indicated that loss of AIM2 in HCC cells contributed to disease progression via mammalian target of rapamycin (mTOR)-S6K1 pathway activation, which may pave a new avenue to treat AIM2 deficient cancer by suppression of mTOR." (PMID 27167192, 2016). "This study also paves a new avenue to treat AIM2-deficient cancer by suppression of mTOR." (PMID 27167192, 2016). "In addition to the NLR family inflammasomes, AIM2 has also been implicated in cancer growth." (PMID 37497237, 2023). "Additionally, loss of AIM2 expression is associated with oncogenic properties in these cancers." (PMID 33859277, 2021). "This review summarizes the diverse modes through which AIM2 in different cancers and discusses the possible future clinical application of AIM2." (PMID 41811896, 2026). "Here, we reported the recently developed therapeutic approaches targeting the AIM2 inflammasome to affect cancer development." (PMID 40002808, 2025). "The presence of dsDNA-containing exosomes in (cancer) cells is considered an oncological biomarker and DNA release by cancer cells activates AIM2 in macrophages." (PMID 40356602, 2025). "Research has been demonstrated that the overexpression of AIM2 lead to the promotion of apoptosis and the suppression of migration and invasion in cancer cells by inhibiting the Notch signaling pathway." (PMID 39744568, 2025). "Cui and co-workers recently highlighted the significance of AIM2 inflammasome activation in cancer treatment, emphasizing development of effective immunotherapeutic approaches targeting AIM2 modulation." (PMID 40356602, 2025). "In the context of cancer, AIM2 either inhibits or promotes tumorigenesis in an inflammasome-dependent or inflammasome-independent manner." (PMID 41062723, 2025). "Overall, AIM2’s involvement in RCC highlights the complexity of cancer biology and the need for integrated approaches to treatment." (PMID 40386782, 2025). "Prior research has primarily concentrated on the involvement of AIM2 in different types of cancer, particularly in relation to inflammasome signaling." (PMID 39744568, 2025).
cancer (continued). "The recognition of dsDNA by the AIM2 inflammasome either in cancer cells or in immune cells can further exacerbate inflammatory processes on the basis of cancer progression." (PMID 40002808, 2025). "This review provides a comprehensive overview of recent advancements in understanding the involvement of AIM2 in the pathogenesis of different types of cancer through both inflammasome-dependent and inflammasome-independent mechanisms." (PMID 39744568, 2025). "In conclusion, the regulatory mechanism of AIM2 in cancer development and progression holds significant potential as a therapeutic target for the treatment of various cancers." (PMID 39744568, 2025). "AIM2 also plays a dual role in cancer progression, functioning through both inflammasome-dependent and independent mechanisms." (PMID 40692785, 2025). "Among the various inflammasomes identified, NLRP3 and AIM2 have emerged among the most extensively characterised in cancer biology." (PMID 41148809, 2025). "This review aims to provide an overview of the controversial role of AIM2 in cancer, taking into consideration the pharmacological tools currently available to modulate AIM2 activity in cancer." (PMID 40002808, 2025). "AIM2 is significantly involved in the initiation and advancement of numerous types of cancer, although its expression and mechanisms vary among different cancer types." (PMID 39744568, 2025). "In summary, this study provides evidence that AIM2, typically recognized as a DNA sensor or gene related to cancer, plays a crucial role in RPE-EMT and proliferation, thereby contributing to the development of PVR in the eye." (PMID 39870644, 2025). "The relevance of the AIM2 inflammasome in several types of tumors suggests the potential benefit of its therapeutic modulation in a range of cancers." (PMID 40002808, 2025). "In conclusion, AIM2 exhibits diverse functions in the pathogenesis of various cancers through its interaction with inflammasome signaling pathways." (PMID 39744568, 2025). "AIM2 plays a multifaceted role in tumorigenesis, demonstrating both promotional and inhibitory effects on cancer development." (PMID 39744568, 2025). "After PTX treatment, the expression of AIM2 significantly increased compared to untreated control suggesting the initiation of cell death program and cancer cell proliferation suppression." (PMID 39433537, 2024). "Elevated SIRT1 expression inhibits the AIM2 inflammasome, a mechanism that suppresses pyroptosis while promoting the proliferation of cancer cells." (PMID 38474460, 2024). "Even nowadays, regarding to essential roles of AIM2 in the condition of autoinflammatory conditions and cancer due to the potential recognition of DNA-RNA hybrids by AIM2 and its activation, AIM2 is an important research point for immunotherapeutic approaches." (PMID 39290706, 2024). "NLRP1, NLRP3, NLRC4, NLRP6, and AIM2 have been demonstrated to influence the pathogenesis of cancer by modulating innate and adaptive immune responses, cell death, and proliferation." (PMID 39684769, 2024). "In defense of the host not only against external pathogens (both viruses and bacteria) but also against the development of inflammatory and autoimmune diseases (e.g. psoriasis) and cancer, the activity of the AIM2 inflammasome plays an important role." (PMID 39290706, 2024). "Providing EVs with AIM2 inflammasome proteins was found to induce pyroptosis in cancer cells by downregulating SIRT1." (PMID 38474460, 2024).
cancer (continued). "For example, it is known that AIM2 can regulate PD-L1, and that IL-1β is able to increase PD-L1 at the membrane of cancer cells and CAFs." (PMID 37819510, 2023). "The immunohistochemistry (IHC) results of the tumors and normal tissues also indicated that AIM2 was increased in cancer tissues." (PMID 36923928, 2023). "In summary, this study shows that macrophage AIM2 is activated by nucleic acids secreted from the cancer cells, which leads to inflammasome activation, IL-1β cleavage and release from macrophages." (PMID 37449203, 2023). "In contrast, cancer cell proliferation and metastasis are suppressed when AIM2 expression is low in patients with cutaneous squamous cell carcinoma and NSCLC." (PMID 37046775, 2023). "The Gasdermin (GSDM) family member genes NLRP3, NLRC4, NLRP1, AIM2, IL-1β, and IL-18 are linked to TIME, and the immunosuppressive microenvironment can be overcome by targeted pyroptosis therapy in cancers." (PMID 36882663, 2023). "The emerging role of AIM2 in the pathogenesis and development of various cancers, has garnered attention." (PMID 38186575, 2023). "Various studies have established that AIM2 plays a critical role in cancer development and progression, displaying both pro-cancer and oncogenic activities." (PMID 37932362, 2023). "Exogenous IL-1β stimulated proliferation of TRAMPC2 cancer cells, and addition of exogenous IL-1β stimulated proliferation of TRAMPC2 cancer cells similarly in the presence of WT and AIM2-/- or Caspase1/11-/- macrophages." (PMID 37449203, 2023). "Remarkably, our bioinformatics analyses indicated a connection between AIM2 expressions and several cancer-related processes and pathways, such as oxidative phosphorylation, focal adhesion, cell cycle, and the MAPK signaling pathway." (PMID 38186575, 2023). "Hypomethylation-induced overexpression of AIM2 has been observed in various types of cancer, including OSCC." (PMID 38067304, 2023). "Our investigation uncovers significant correlations between AIM2 expression and cancer-related processes and signaling pathways, thereby reinforcing AIM2’s involvement in CRC progression, particularly through P38 mitogen-activated protein kinase (P38MAPK)." (PMID 38186575, 2023). "Strikingly, cytosolic DNA is not found in healthy tissues, suggesting that it is a unique cancer phenotype and hence giving us a clue to study the link between cancer cells and AIM2 inflammasome activation." (PMID 37449203, 2023). "Because of the different immune responses of AIM2 inflammasomes, they are considered a double-edged sword in many cancers." (PMID 36248785, 2022). "Over the last decade, numerous studies have documented the importance of AIM2 in inflammation, immune defense against intracellular pathogens and cancer." (PMID 35216346, 2022). "We used the survival curve to explore the prognostic significance of the AIM2 inflammasomes in pan-cancer." (PMID 36248785, 2022). "In summary, we performed the first comprehensive analysis of AIM2 inflammasomes in pan-cancer and found that AIM2 inflammasomes are aberrantly expressed in a variety of methylated tumors." (PMID 36248785, 2022). "For instance, when we use AIM2 inflammasome inhibitors or drugs to treat psoriatic patients also with cancer, in the future, we need to pay attention to its impact on cancer." (PMID 36118867, 2022). "PRGs with consistent enhanced expression and association with poor survival in cancers included GSDMC in BRCA, KIRC, LIHC, PAAD, UVM and KICH; DFNA5 (GSDME) in COAD, STAD, UCEC, HNSC, KIRC; and AIM2 in KIRP, KIRC, UVM, and PAAD." (PMID 36605187, 2022). "We further investigated the pan-cancer expression levels of the AIM2 inflammasomes scores at different stages." (PMID 36248785, 2022). "For development of a cancer treatment strategy targeting AIM2, clinicians must take into consideration the role of AIM2 in different types of cancer." (PMID 35734577, 2022).
cancer (continued). "Later explorations revealed that the antitumorigenesis effects of AIM2 are relevant to multiple types of cancer." (PMID 36086707, 2022). "We performed a pan-cancer analysis of AIM2 in multiple cancer types using The Cancer Genome Atlas (TCGA) database." (PMID 36248785, 2022). "Studies over the past decades have shown that AIM2 inflammasome plays a vital role in many kinds of inflammatory diseases, immune diseases, and cancers." (PMID 36118867, 2022). "Although it is generally acknowledged that inflammation plays a critical role in cancers, the effect of the AIM2 inflammasome in tumorigenesis is still unclear." (PMID 36386141, 2022). "AIM2 expression patterns vary from one carcinoma to another, which meant it played a special role in different kinds of tumors." (PMID 36276158, 2022). "Staining for either BCL2A1 or AIM2 revealed that both are correlated with pN status, extranodal extension, clinical stage and cancer-specific survival (CSS)." (PMID 33391539, 2021). "The function of AIM2 in innate immunity and inflammation has been well investigated, but its role in cancer remains to be elucidated." (PMID 33842454, 2021). "AIM2 was differentially expressed in multiple cancers, including bladder, breast, esophageal, kidney, liver, lung, stomach, and endometrium, as well as CASP5, NOD2, and GZMB." (PMID 34906145, 2021). "It is widely accepted that the expression level of NLRP3 and AIM2 can predict the inflammasome signaling activity in cancers." (PMID 34815793, 2021). "Absent in melanoma 2 (AIM2), an important inflammasome component, was initially identified in cancer‐associated studies and has been reported to suppress many types of cancer." (PMID 34156153, 2021). "Among them, the expression of AIM2/ASC/IL-18, MyD88, DAI, DHX36, and DDX60 were associated with cancer stages." (PMID 31949493, 2020). "AIM2 plays a different role and acts via different signalling pathways under different circumstances according to studies regarding cancer that have been previously published." (PMID 33162829, 2020). "Since the role and activation of AIM2 are different in each type of cancer, the drug discovery for the therapeutic target of the AIM2 inflammasome should be conducted carefully." (PMID 32121297, 2020). "Several studies have shown that the AIM2 inflammasome has a peculiar protective role in BC in that it enhances apoptosis and suppresses cancer cell proliferation by inhibiting NF-kB activity." (PMID 33014808, 2020). "In cancer, increased expression of AIM2 has been reported in nasopharyngeal carcinoma tumors, oral squamous cell carcinoma, and lung adenocarcinoma." (PMID 32121297, 2020). "Since AIM2 inflammasome-associated DNA-sensing pathways are closely related to tumorigenesis, future studies are warranted to assess the role of TRIM11 in cancer." (PMID 32703253, 2020). "Inspired by the role of AIM2 in cancer research, we focused our study on FLS, which mimics the cancer cell biobehaviours of proliferation and invasion and is currently regarded as a crucial effector in the pathogenesis of RA." (PMID 33162829, 2020). "AIM2 also promotes NSCLC via modulating mitochondrial dynamics to promote mitochondrial ROS that promotes MAPK/ERK signaling required for cancer cell growth and proliferation." (PMID 33643304, 2020). "Of these, NLRP1, NLRP3, NLRC4, NLRP6, and AIM2 influence the pathogenesis of cancer using various mechanisms of action." (PMID 33614494, 2020). "There are some reports that involved in the correlation between AIM2 expression and cancer progression." (PMID 30833546, 2019). "Cancer cells express well-known PRRs—DNA sensors, such as absent in melanoma 2 (AIM2) and toll-like receptor 9 (TLR9)." (PMID 31205871, 2019).
cancer (continued). "Several inflammasomes including NLRP3, NLRP1, NLRC4, pyrin and AIM2 play a vital role in cancer pathogenesis through their regulation of immunity and apoptosis." (PMID 31492049, 2019). "In the future, we would further investigate the mechanism of AIM2 inflammasome on the side of cancer cell apoptosis." (PMID 30160343, 2018). "Quantification of AIM2 levels in all samples showed a higher mean value of AIM2 protein expression in both cancer types than in ES." (PMID 29423077, 2018). "The results present evidence that AIM2 expression was decreased in RCC tissues compared with normal cancer tissues." (PMID 30160343, 2018). "In consistence with this study, AIM2 was described to limit proliferation and tumorigenecity in colon, breast, and prostate cancers." (PMID 27167192, 2016). "Next we analyzed the expression levels of NLRs and AIM2 at various stages of cancer progression in the TCGA database." (PMID 26378020, 2015). "Nonetheless, we provide strong evidence that the chemoradiotherapeutic activation of the NLRP3 and AIM2 inflammasomes, via cathepsin B and ROS, is likely to emerge as a crucial player in the regulation of cancer immunotherapy." (PMID 23065753, 2012). "In order to delineate the function of inflammasomes in other cancer types, we evaluated the expression patterns of AIM2, RIG-I, NLRP3, ASC and caspase-1 in 114 cancer cell lines involving 22 cancer types." (PMID 23065753, 2012). "AIM2 functions as a significant regulatory factor in the context of cancer." (PMID 39744568, 2025). "Consequently, understanding the mechanisms governing AIM2 regulation in cancer development and progression represents a promising therapeutic strategy for various malignancies, albeit with significant challenges." (PMID 39744568, 2025). "AIM2 functions as a dsDNA sensor that initiates inflammasome signaling in various cancer types." (PMID 39744568, 2025). "Additionally, AIM2 inhibits EMT or proliferation in other cancer types, such as hepatocellular carcinoma and breast cancer." (PMID 39870644, 2025). "AIM2 has been shown to enhance cancer cell proliferation through the regulation of mitochondrial dynamics, leading to reduced mitochondrial fusion and subsequent elevation of cellular reactive oxygen species (ROS) production and activation of the MAPK/ERK signaling pathway." (PMID 39744568, 2025). "Therefore, this review will primarily focus on NLRP3 and AIM2 inflammasomes in the context of cancer-related EMT and its therapeutic modulation." (PMID 41148809, 2025). "This review highlights AIM2 as the initial non-NLR family inflammasome implicated in various cancer types, underscoring its significant involvement in tumorigenesis irrespective of inflammasome activation." (PMID 39744568, 2025). "Similar to AIM2 and NLRP3, NLRC4 is implicated in various types of cancer." (PMID 40692785, 2025). "Furthermore, AIM2 has the potential to impact cancer development through either an inflammasome-dependent or inflammasome-independent mechanism." (PMID 39744568, 2025). "These dynamics could be attributed to the observed downregulation of AIM2 in certain cancer scenarios." (PMID 38693119, 2024). "The oncogenic role of AIM2 remains controversial in different cancer types." (PMID 38166970, 2024). "This demonstrates that all cancer cell lines could stimulate AIM2 inflammasome activation in macrophages exposed to the conditioned media from these cell lines." (PMID 37449203, 2023). "Lastly, the functional modalities of genes are often multifaceted and complex, and our analysis might have only partially revealed the various roles of AIM2 in the context of cancer." (PMID 37932362, 2023). "Similarly, breast cancer, hepatocellular carcinoma, and renal cell carcinoma exhibit low levels of AIM2 expression, promoting cancer cell proliferation and metastasis." (PMID 37046775, 2023).